ENSG00000212273
Synonyms: LOC124900268
Gene: Small nucleolar RNA gene on chromosome 8 (133,644,598 to 133,644,725, reverse strand). Ensembl gene ENSG00000212273.
Gene Ontology:
Biological process: RNA processing
Cellular component: nucleolus
Homologues: Paralogues in human: SNORA40B (93% identical), SNORA40 (91% identical), SNORA40C (88% identical).